IL10 (interleukin 10)
Diseases named in the same sentence as IL10 in open-access papers (continued):
Sharing a sentence is not in itself a finding about the gene and the disease.
colitis (continued). "Interestingly, IL-10 and TLR4 double knockout mice have an accelerated colitis development compared to IL-10 and TLR9 double knockout and IL-10 single knockout which do not develop colitis." (PMID 23382912, 2013). "Indeed, we found that in the IL-10−/− mice there was an overproduction of IFN-γ and IL-17, whereas in DSS-induced model of colitis occurred a prevalence of IL-6, TNF-α, and INF-γ without alterations in IL-17 production (data not shown)." (PMID 22400037, 2012). "This issue is manageable, however, given that patients who develop or did not develop colitis after anti-CTLA-4 therapy have distinct microbial communities, IL-10−/− mouse models show Bifidobacteria may prevent colitis after anti-CTLA-4 therapy, and FMT may prove effective." (PMID 32487228, 2020). "The findings that butyrate-treated Prdm1−/− Th1 cells produced lower levels of IL-10 and were not able to control colitis as effectively as butyrate-treated WT Th1 cells indicate the importance of Blimp-1-mediated SCFA induction of IL-10 production in controlling colitis development." (PMID 30177845, 2018). "However, treatment with the high dose of cis-UCA did significantly decrease colonic tissue IFN-γ levels compared to treatment with PBS control and low dose cis-UCA during colitis in IL-10−/− mice, suggesting a cis-UCA-induced modulation of T cell function, even in the absence of IL-10." (PMID 21060867, 2010). "In addition, adoptive cell transfer of CD69+ Treg, but not CD69− Treg or CD69+ Treg from IL10−/− mice, reduced DSS-induced colitis severity in mice, suggesting WPI exposure may increase immune tolerance via induction of Treg with enhanced suppressive capacities." (PMID 36678267, 2023). "Considering that in our experiments Park7 gene silencing did not alter expression of Il10, we suggest that decreased colonic expression of Il10 may be rather an indirect consequence of decreased inflammation, observed in Comp23 treated mice with DSS induced colitis." (PMID 34272410, 2021).
COVID-19 (1,286 papers, 2020 to 2026). A disease caused by infection with severe acute respiratory syndrome coronavirus 2. "It has been reported that IL-6, IL-8, and IL-10 are associated with systemic inflammation and are increased in patients with COVID-19-related ARDS." (PMID 36817433, 2023). "The propagation of systemic of systemic inflammation by CD8+ T cell derived cytokines (e.g., IFNγ) would presumably be bolstered by IL-10 mediated activation of tissue-resident mast cells, which are abundant in lung epithelial membranes and have been implicated in COVID-19-related inflammation." (PMID 34234779, 2021). "Co-infection also triggered robust increases in IFN-γ and IL-1β, whereas malaria alone was associated with higher IL-6, IL-4, and IL-10, and COVID-19 alone was associated with elevated IL-2 and TNF-α." (PMID 41758897, 2026). "A marked elevation of IL-10 is a hallmark of severe COVID-19, distinguishing it from other betacoronavirus infections such as SARS and MERS." (PMID 41596316, 2026). "In cases of ARDS associated with COVID-19, the co-occurrence of high levels of IL-10 and LPS can lead to a state of hyper-inflammation." (PMID 40761632, 2025). "Six genes, including TNF, CXCL8, IL-6, IL-1β, IL-2, and IL-10, were associated with three major signaling pathways: the COVID-19 adverse outcome pathway, an overview of pro-inflammatory and pro-fibrotic mediators, and the interleukin-10 signaling pathway." (PMID 40166075, 2025). "Higher IL-6 serum concentrations (p=0.03) were associated with more severe COVID-19, and higher serum IL-10 concentrations, (p=0.03) with mortality." (PMID 40352457, 2025). "When comparing the serum concentrations of TNF-α and IL-10 between HCs and patients, it was found that patients with moderate and severe ARDS caused by COVID-19 had significantly higher levels of IL-10 (P < 0.001)." (PMID 40761632, 2025). "In the case of hypoxic conditions usually seen in patients with COVID-19, the effect of IL-10 on macrophages can be altered and cause an increase in pro-inflammatory cytokines like IL-6 via the activation of the hypoxia-inducible factor (HIF) pathway." (PMID 39940645, 2025). "High levels of both IL-6 and IL-10 were found in critically ill COVID-19 patients, which were at the highest risk of death." (PMID 40508859, 2025). "Early production of IL-10 in SARS-CoV-2 infection has been associated with the severity of COVID-19, since elevated levels of IL-10 can influence the production of cytokines responsible for the resolution of the infection." (PMID 39859379, 2025). "Overall, these results suggest that severe COVID-19 is associated with elevated IgE and IL-10 levels, whereas mild disease is characterized by lower IgE and relatively higher IgG concentrations." (PMID 41157211, 2025). "A binary logistic regression analysis model showed that pneumonia caused by COVID-19 was associated with levels of IL-6 > 16 pg/ml (OR = 4.02; p < 0.01; 95% CI = 1.43–11.34) and IL-10 > 3 pg/ml (OR = 9.36; p < 0.01; 95% CI = 3.21–21.44)." (PMID 40508859, 2025). "In both cases, the IL-10 overproduction seen in patients with COVID-19 causes more damage than good." (PMID 39940645, 2025). "Conversely, significantly lower GSR and elevated levels of IL-10 in COVID-19 patients suggest deficiencies in antioxidant capabilities and immune function, respectively." (PMID 41583455, 2025). "Given that liver injury was associated with coagulation dysfunction, high Il10 expression was verified to closely link to adverse outcomes in both dengue fever and COVID-19." (PMID 40623122, 2025). "The current study aims to assess the association of COVID-19 severity and mortality with the relative expression of MicroRNA-155 (miR-155) and its association with serum levels of interleukin (IL)-6, IL-10, and their derived ratio." (PMID 41203712, 2025). "Recent studies have also highlighted strong associations between SNPs of IL6 (rs2069840) and IL10 (rs1800872) genes and the severity of COVID-19." (PMID 40881695, 2025).
COVID-19 (continued). "COVID-19 severity is linked to elevated levels of inflammatory mediators, including cytokines (e.g., IL-2, IL-7, IL-10, IFN-γ, and TNF-α) and chemokines (e.g., G-CSF, MCP1, MIP1α, and CXCL10), as well as markers like C-reactive protein, ferritin, and D-dimers." (PMID 40649865, 2025). "Overall, we identified independent risk factors for mortality in patients with COVID-19 treated with glucocorticoids and used these prognostic factors—diabetes, ferritin, and IL-10—to develop a nomogram model." (PMID 41426569, 2025). "COVID-19 patients possessing the –1,082 A/G single nucleotide IL-10 GG and GA genotypes and the G allele presented with less severe ARDS." (PMID 40761632, 2025). "This study identified obesity as a key biological factor that exacerbated COVID-19, demonstrating a direct association between increased BMI, elevated Ang II, and heightened pro-inflammatory cytokines, alongside reduced IL-10." (PMID 41562075, 2025). "The anti-inflammatory cytokine IL-10 was positively associated with odds of hospitalization or death from COVID-19 and mediated 2% of the TNFR1 association." (PMID 41280118, 2025). "This inflammation, driven by pro-inflammatory cytokines (interleukin-6 (IL-6), IL-1, IL-2, IL-10, tumour necrosis factor alpha, interferon-γ) and coagulation dysfunction, is thought to be the main cause of COVID-19-associated myocarditis." (PMID 40502868, 2025). "Our results showed that 2 inflammatory proteins (interleukin-10 and interleukin-18) were positively associated with COVID-19 risk, while 1 inflammatory protein (PD-L1) was negatively associated." (PMID 40101060, 2025). "The consistent association of elevated IL-6, IL-10, and S100B levels with severe disease outcomes points to their potential use in stratifying COVID-19 patients based on risk." (PMID 41585373, 2025). "A meta-analysis of 77 prospective or retrospective cohort studies in adult patients with COVID-19 showed that IL-1β, IL-2R, IL-4, IL-6, IL-8, IL-10, and IL-17, inflammatory markers, were potential risk factors for severe SARS-CoV-2 infection or mortality." (PMID 40066463, 2025). "Although elevated IL-10 is associated with severe disease in many viral infections including dengue, compared to illnesses such as severe COVID-19, the IL-10 levels in those who have DHF are several folds higher." (PMID 39232783, 2024). "In the recessive inheritance model, a statistically significant association was observed between the IL-10 GG genotype and susceptibility to COVID-19 (OR=2.49, 95% CI=1.0797 - 5.746, RR 1.46, and p = 0.022)." (PMID 38544825, 2024). "Elevated levels of IL-10 are associated with T-cell apoptosis in acute dengue and T-cell exhaustion in COVID-19, presumably via overactivation and proliferation." (PMID 39583156, 2024). "Background/Objectives: Severe clinical course and mortality from COVID-19 are mostly associated with increased concentrations of IL-6 and IL-10." (PMID 39518552, 2024). "Paradoxically, we found that the CA and CC genotypes of the IL-10 (-592) rs1800872 C>A polymorphism confer significant protection against mortality from COVID-19." (PMID 38544825, 2024). "Inflammation in COVID-19 is predictive of mortality and is associated with increased plasma concentrations of several cytokines including IL-2, IL-6, IL-7, IL-10, and TNF-α." (PMID 39345212, 2024). "Severe COVID-19 is associated with a cytokine storm characterized by elevated plasma concentrations of interleukins (IL-1ß, IL-2, IL-6, IL-7, IL-8, IL-10 and IL-17), interferons, monocyte chemoattractant protein 1 (MCP-1) and TNF-alpha." (PMID 38732160, 2024). "In humans with SARS-CoV-2 infection IL-10 has been associated with severe COVID-19 in multiple studies." (PMID 38950078, 2024). "The haplotypes for the IL-10 polymorphisms showed that the CG haplotype was more frequent in COVID-19 patients (p < 0.0001, OR = 16.97, CI = 6.36–45.29)." (PMID 38287362, 2024).
COVID-19 (continued). "Others showed positive associations between salivary viral load (VL) and COVID-19-related pro-inflammatory markers; IL-6, IL-18, IL-10, and CXCL1028." (PMID 39294156, 2024). "Elevated levels of inhibitory cytokines, such as IL-1RA and IL-10 has been observed in COVID-19 patients with severe outcomes, highlighting their association with disease progression." (PMID 38568894, 2024). "Cytokines like interleukin (IL) IL-10, IL-17A, and IL-1β play pivotal roles in the inflammatory response associated with severe COVID-19." (PMID 39062105, 2024). "Of the 105 cytokines profiled in this study, nine were previously reported to be involved in the cytokine storm associated with COVID-19 including the following: IL-2, IL-4, IL-6, IL-10, G-CSF, IP-10, MCP-1, TNF-α, and IFN-γ." (PMID 39062978, 2024). "IL-10 and TNFa polymorphisms should be considered for clinical and epidemiological evaluation of COVID-19 patients." (PMID 38287362, 2024). "Elevated IL-10 levels in severe COVID-19 have been linked to worse outcomes and AKI, as observed in our study." (PMID 39485788, 2024). "Another striking feature is the inverse association we found between the development of severe COVID-19 and sera levels of IL-10." (PMID 39194742, 2024). "Our study further investigated serum levels of CRP, IL-1α, IL-6, and IL-10 as predictive markers for identifying patients at risk of worsening COVID-19." (PMID 39338474, 2024). "At the same time, those patients infected with COVID-19 exhibited a reduced total number of T cells and increased concentrations of IL-6 and IL-10, which are risk factors that aggravate the severity of COVID-19 in patients with lung cancer." (PMID 39308869, 2024). "Our data is the first to unravel the association between polymorphisms in IL-10 gene promoter and COVID-19 in an Egyptian population, which gives insight into the genetic diversity of immune responses towards SARS-COV2." (PMID 38287362, 2024). "Meanwhile, an elevated level of IL-6 and IL-10 is associated with unfavorable prognosis for COVID-19 patients." (PMID 38173531, 2024). "Severe COVID-19 has been chiefly associated with inflammatory cytokines such as interleukin 6 (IL-6), IL-8, and IL-10 overexpression." (PMID 38375062, 2024). "Elevated IL-1β, IL-6, IL-8, IL-10, and IL-17 in plasma is associated with disease severity in COVID-19 patients." (PMID 39739157, 2024). "Our research showed significant associations between inflammatory markers such as NLR and IL-10 and the period of time from the end of COVID-19 treatment to the start of rehabilitation." (PMID 39335569, 2024). "This is consistent with previous data that have shown that, in particular, IL-10 and IL-2 levels are higher in COVID-19 patients and associated with disease severity." (PMID 37175392, 2023). "Cytokines (IL-2R, IL-6, IL-8, TNF-α, and IL-10) were significantly associated with in-hospital mortality in COVID-19 patients." (PMID 37735372, 2023). "Inflammation in COVID-19 patients is associated with up-regulation of interleukin (IL)-2, IL-6, IL-10, granulocyte colony-stimulating factor (G-CSF), interferon-inducible protein 10 (IP-10), monocyte chemoattractant protein 1 (MCP1)." (PMID 36814234, 2023). "The original levels of five cytokines were statistically significantly associated with COVID-19 mortality, i.e., IL-6 (p < 0.001), IL-2R (p < 0.001), IL-8 (p < 0.001), IL-10 (p < 0.001), and TNF-α (p < 0.05)." (PMID 37735372, 2023). "Of these, it is noteworthy that elevated IL-1RA and IL-10 have been associated with severe COVID-19, likely reflecting an attempt by the host to mount a protective response." (PMID 37786945, 2023). "The COVID-19 mortality rate was associated with IL10 rs1800872 TT genotype in the Alpha and Omicron BA.5 variants and GT in the Alpha and Delta variants." (PMID 36882862, 2023).
COVID-19 (continued). "Although this pathogenic process is shared between COVID-19 and the other beta-coronavirus infections, the massive increase of IL-10 levels in patients with severe forms of the illness is a clinical feature that uniquely distinguishes SARS-CoV-2 infections." (PMID 37359549, 2023). "This study found that IL10 gene polymorphisms rs1800871, rs1800872 and rs1800896 were linked to COVID-19 mortality in different SARS-CoV-2 variants in the Iranian population." (PMID 37237997, 2023). "Orumaa and co-authors revealed that severity of COVID-19 is linked to cytokine storm, which occurs when levels of inflammatory mediators such as IL-7, IL-10, and MIP are up-regulated." (PMID 37053191, 2023). "Increased levels of IL-6 and IL-10 were associated with a high risk of severe liver damage in COVID-19 patients." (PMID 37251383, 2023). "The findings of the present study revealed that the COVID-19 mortality rate was associated with the IL10 rs1800872 TT genotype in Alpha and Omicron variants and GT in Alpha and Delta variants." (PMID 36882862, 2023). "In IL10 rs1800872 and rs1800896 polymorphisms, the patients with TT and GG genotypes had a higher COVID-19 death rate." (PMID 36882862, 2023). "In patients with COVID-19, the allele C (0.36) for the IL10 rs1800871 as MAF was directly correlated with death." (PMID 36882862, 2023). "In this study, IL10 haplotype distribution indicated that the frequency of the TCG haplotype among the deceased COVID-19 patients in three different SARS-CoV-2 variants was higher than in the recovered subjects." (PMID 36882862, 2023). "Although IL-10 is known for its immunomodulatory effects, it has also been seen to be elevated in COVID-19 patients and associated with COVID-19 severity." (PMID 37175392, 2023). "has reported higher IL-6 and IL-10 levels in serum of adults over 65 with COVID-19, associated with disease severity and a higher comorbidity index." (PMID 37359549, 2023). "The first possible explanation of the COVID associated data, suggests in fact that IL-10, in the context of ongoing inflammation induced by COVID-19, behaves in a canonical way as an anti-inflammatory and immunosuppressive cytokine." (PMID 37359549, 2023). "The IL-10 mutation rs1800872 has been found to increase the susceptibility of individuals to both periodontitis and COVID-19." (PMID 37568161, 2023). "Although considered a major anti- inflammatory cytokine, early rise of IL-10 is associated and possibly involved in severe COVID-19." (PMID 37674148, 2023). "The tumor necrosis factor (TNF-α), IL-6, and IL-10 concentrations are the most important mediators of cytokine storm formation, and their levels clearly distinguish mild from severe cases of COVID-19 and are associated with poor prognosis of the disease." (PMID 37759873, 2023). "Тhus, it should be noted that this study complements the current knowledge about the association of IL10 rs1800872 gene polymorphism with the biomarker of immunothrombosis and the severity of COVID-19." (PMID 37390087, 2023). "Allelic and genotypic analysis of polymorphisms of the studied cytokine genes showed an association between IL10 rs1800872 and the severity of COVID-19." (PMID 37390087, 2023). "Our findings indicate that IL-6, IL-8, and IL-10 serum levels are significantly increased in COVID-19 but are associated with poor predictive ability regarding disease severity and the need for oxygen therapy." (PMID 37969879, 2023). "Further PPI network analysis, differential analysis, and molecular docking revealed that the critical component quercetin affects the inflammatory response caused by COVID-19 through the core targets IL-6 and IL-10." (PMID 38050310, 2023). "The significant increase in IL-10 is a distinguishing hallmark of the cytokine storms occurring in COVID-19." (PMID 38139439, 2023). "The IL10 rs1800871 CC genotype was correlated with a higher risk of COVID-19 mortality (P < 0.0001, OR 3.59, 95% CI 2.82–4.56)." (PMID 36882862, 2023).